TRAF7 (TNF receptor associated factor 7)
Diseases named in the same sentence as TRAF7 in open-access papers (continued):
Sharing a sentence is not in itself a finding about the gene and the disease.
meningioma (continued). "Beyond germline mutations associated with TRAF7 syndrome and developmental delays, pathological somatic mutations also occur in TRAF7, which are associated with subsets of meningiomas, mesotheliomas, intraneural perineuriomas, and adenomatoid tumors of the genital tract." (PMID 41372821, 2025). "TRAF7 mutations in meningioma co-occur either with mutations in Kruppel-like factor 4 (KLF4) or in other genes, including v-Akt murine thymoma viral oncogene homolog 1 (AKT1) or phosphatidylinositol-4,5-bisphosphate 3-kinase catalytic subunit alpha (PIK3CA) variants." (PMID 41372821, 2025). "Our peer-reviewed paper, citing only the original study with TRAF7 germline mutations, reported significant genetic and biochemical research beyond the clinical genetics correlating TRAF7-related ciliary defects in meningiomas and CHD and broadened the disease spectrum." (PMID 38466853, 2024). "The most common genetic aberration in meningiomas is functional loss of NF2 and occurs in both low- and high-grade meningiomas, whereas NF2-wildtype meningiomas are enriched for recurrent mutations in TRAF7, KLF4, AKT1, PI3KCA, and SMO and are more frequently benign." (PMID 38571886, 2024). "In addition to developmental disorders, TRAF7 somatic variants are also involved in multiple tumors, mainly meningioma and mesothelioma." (PMID 38178633, 2024). "Interestingly, meningiomas with mutations in TRAF7, KLF4, AKT1 and SMO, as well as POLR2A, were later described by Nassiri and colleagues to have a more favorable patient prognosis compared to other genetic driver mutations." (PMID 39273576, 2024). "Moreover, it is relevant to develop new GEMMs that explore targetable somatic mutations found in human meningiomas such as TRAF7, AKT1, and PIK3CA, among others." (PMID 38001599, 2023). "Additionally, TRAF7 mutations instigate meningioma growth by acting in combination with one of various co-mutations such as KLF4 and AKT1." (PMID 38001599, 2023). "One of the reasons might be that TRAF7 mutants expressed in hemizygous meningioma cells foster partial loss of normal TRAF7 function through the formation of dysfunctional hetero-trimers consisting of normal and mutant TRAF7 proteins." (PMID 36937440, 2023). "CNVs deleting NF2 on chromosome 22q are early events underlying Immune-enriched or Hypermitotic meningioma tumorigenesis, but Merlin-intact meningiomas encode SSVs targeting TRAF7, AKT1, or KLF4 that may be tumor-initiating." (PMID 36993679, 2023). "Likewise, KLF4 mutations seem to occur only in NF2-intact meningiomas and frequently co-exist with alterations of TRAF7." (PMID 36181606, 2023). "To investigate whether high expression of genes in TRAF7 meningiomas resulted from loss of TRAF7 function, we examined expression of several of them in TRAF7-deficient mouse embryonic fibroblasts (MEFs)." (PMID 36937440, 2023). "Merlin-intact meningiomas can encode somatic short variants (SSVs) targeting TRAF7, PIK3CA, AKT1, KLF4, or the Hedgehog pathway, but some of these variants may be passenger mutations that do not influence meningioma tumorigenesis." (PMID 36993679, 2023). "Among the non-NF2-mutated group, the most common oncogene in WHO grade I meningiomas is TNF receptor-activated factor 7 (TRAF7), located on chromosome 16p13 (mutated in nearly 25% of all meningiomas), followed by the mutation in codon K409Q of KLF4 (encountered in about 15% of benign meningiomas)." (PMID 37760490, 2023). "Studies have identified driver TRAF7 somatic mutations in meningioma tumorigenesis." (PMID 38001599, 2023).
meningioma (continued). "TRAF-7 mutated meningiomas demonstrated elevated levels of programmed death ligand-1 (PD-L1), the major ligand for the programmed death checkpoint pathway, while PD-L2 is highly expressed in PI3K/AKT/mTOR pathway mutations and CTLA-4 was frequently expressed in PIK3CA and SMO mutated tumors." (PMID 36033542, 2022). "Importantly, the rest of the tumor samples, including meningiomas harboring only TRAF7 mutation or together with mutations in genes other than KLF4, had no detectable levels of FGF3 mRNA." (PMID 35996584, 2022). "Irrespective of the histological grade, most meningiomas (55%) exhibit NF2 alterations, while NF2 wild-type meningiomas may harbor mutations in TRAF7, KLF4, PIK3CA or SMO." (PMID 35049691, 2022). "The analyses here were initiated after diagnostic work-up of the tumors of a 47-year-old male patient with two independent meningiomas having identical somatic TRAF7 mutation N520S, but separate AKT1 (skull base, meningothelial) and KLF4 (convexity, secretory type) hotspot mutation." (PMID 35984495, 2022). "Interestingly, different mechanisms play a role between BI and bone invasion in some meningioma subtypes, depending on tumor location and genomic features and, among them, NF-2 and TRAF7 mutations." (PMID 36077700, 2022). "TRAF7 mutations were detected in up to 25% of grades 1 and 2 meningiomas." (PMID 35565385, 2022). "In contrast, we could not find in our WHO grade 1 tumors and control populations, non-synonymous genetic variants, for other genes previously reported to be recurrently mutated in meningiomas such as the TRAF7, AKT1, KLF4, TERT, and PIK3CA genes." (PMID 34868937, 2021). "TRAF7 mutations are seen in up to ~25% of meningiomas and in all of the secretory subtypes." (PMID 33801089, 2021). "New GEMMs are needed in order to explore targetable somatic mutations found in human meningiomas, such as TRAF7, AKT1 or PIK3CA, where they will be essential for understanding the specific biological mechanisms involved and to provide accurate tools for preclinical drug evaluation." (PMID 34359639, 2021). "Furthermore, KLF4 and TRAF7 seem to be associated with secretory meningiomas with more aggressive behavior due to increased swelling of the brain." (PMID 34679551, 2021). "In addition to tumor location, KLF4/TRAF7 mutations are independently correlated with secretory histopathology, with nearly all secretory meningiomas harboring this combination of mutations." (PMID 34638590, 2021). "In NF2 wild-type meningiomas, mutations in TRAF7, KLF4, AKT1, and SMO were noted." (PMID 34778063, 2021). "According to the literature, TRAF7 is the most often affected gene in non-NF2 mutated meningiomas." (PMID 31470906, 2019). "In particular, high frequencies (15–26%) of TRAF7 mutations has been reproducibly detected in multiple studies, and knowledge of TRAF7 mutations has contributed significantly to improving the diagnosis, classification, prognosis, and treatment of patients with meningiomas." (PMID 30294322, 2018). "Other mutations associated with meningiomas (ARID1A, SMO and TRAF7) were also restricted to sporadic meningiomas, suggesting that radiation therapy induces tumorigenesis through a different set of genetic alterations to those of sporadic meningioma." (PMID 28775249, 2017). "Loss of TRAF7 in meningeal cells promoted the activity of CDC42 and the p21-activated kinase PAK1 and enhanced RAS activity and the upregulation of the MAPK cascade in meningioma cells, suggesting that these pathways might be important in TRAF7-mutated meningiomas." (PMID 38571886, 2024).
meningioma (continued). "The WD40 domain of TRAF7 has recently emerged as a common mutational hot spot for a subset of unusual human tumors, including mesotheliomas, adenomatoid tumors of the genital tract, fibromyxoid spindle-cell sarcomas of soft tissue, perineurioma nerve sheath tumors, and meningiomas (49, –, 51)." (PMID 38814079, 2024). "In accordance with previous findings, mutations in SMO, KLF4, AKT1, PIK3CA, and TRAF7 were exclusive to the benign methylation class, suggesting that their presence could be used as a surrogate for the methylation profile to identify benign meningiomas." (PMID 37296907, 2023). "Interestingly, about 50% of all AKT1-mutated meningiomas also show alterations in TRAF7." (PMID 38137885, 2023). "However, little is known about the role of mutated TRAF7 in meningioma development." (PMID 35996584, 2022). "A proportion of meningiomas at the middle skull base (ranging between 2.1% and 24%, and between 8.6% and 11.8%, respectively) were reported to display TRAF7 and KLF4K409Q mutations, which co-occur in secretory meningiomas, and which may coexist with AKT1 mutations." (PMID 34071391, 2021). "In addition, recent genomic analyses of meningioma using next-generation sequencing have identified mutations in the TNF receptor-associated factor 7 (TRAF7), the Kruppel-like factor 4 (KLF4), the v-Akt murine thymoma viral oncogene homolog 1 (AKT1), and the smoothened (SMO) gene." (PMID 32742192, 2020). "There has been extensive work aiming to elucidate the mechanism of meningioma development in tumors with TRAF7 alterations." (PMID 41372821, 2025). "We propose that TRAF7-mutant meningiomas possess synthetic lethal vulnerabilities in MAPK or ER stress signaling, which can be discovered by lineage-specific CRISCR screening in meningeal models." (PMID 40867323, 2025). "TRAF7 has previously been identified in NF2-independent meningiomas, malignant mesothelioma, and in small numbers of clear cell, papillary, and chromophobe RCCs." (PMID 40510153, 2025). "TRAF7 (along with NF2 and PI3K) associated meningiomas are more aggressive and recur at a significantly higher rate than other molecular subgroups of meningiomas (KLF4, POLR2A, and SMARCB1)." (PMID 41372821, 2025). "Somatic TRAF7 mutations, when they occur in conjunction with mutations in the KLF4 gene, are associated with secretory meningioma development." (PMID 41372821, 2025). "TRAF7, SMO, AKT1, and KLF4 mutations, referred to as “non-NF2,” are typically found in lower-grade meningiomas, characterized by fewer chromosomal abnormalities, and generally result in better clinical outcomes." (PMID 40725113, 2025). "The molecular characterization of meningiomas has led to the identification of key tumor-driving mutations, including NF2, POLR2A, TRAF7, KLF4, AKT1, SMARCB1, SMARCE1, and SMO." (PMID 39941893, 2025). "Over 80% of sporadic meningiomas fall into one of seven molecular subgroups, including NF2, TRAF7, SMARCB1, KLF4, and mutations in Hedgehog and PI3K pathways." (PMID 40637916, 2025). "Secretory meningiomas, which make up approximately 3% of all meningiomas, are characterized by combined Kru ̈ppel-like Factor 4 (KLF4)K409Q and TRAF7 mutations." (PMID 38879686, 2024). "Mutations in the genes AKT1, SMARCB1, and SMO are rare in cases of atypical meningiomas, and mutations in the genes KLF4 and TRAF7 are associated with an indolent clinical behavior, thus making these meningiomas have a low risk of progression." (PMID 39202270, 2024). "Meningiomas with KLF4 or PI3K pathway variants nearly always harbor a concomitant mutation in TRAF7, which occurs in the WD40-repeat region of TRAF7." (PMID 38730704, 2024). "MI meningiomas, analogous to MG2 cases (NF2-wild type), were largely benign tumors enriched for non-NF2 mutations such as TRAF7, AKT1, and KLF4." (PMID 38695575, 2024). "Other genetic alterations, exclusive of NF2 that are reported in sporadic adult meningiomas, include TRAF7, SMO, KLF4, AKT1 and PIK3CA." (PMID 39612013, 2024).
meningioma (continued). "FD is caused by a mosaic activating pathogenic variant in GNAS gene, and the development of sporadic meningiomas also has genetic predisposition including NF2, TRAF7, KLF4, AKT1 and TERT." (PMID 38287340, 2024). "Previous investigations have identified Wnt pathway activation across meningiomas with SSVs targeting TRAF7, KLF4, PIK3CA, POLR2A, the Hedgehog pathway, and even NF2 and SMARCB125." (PMID 39251601, 2024). "Mutations outside the TRAF7 WD40 region are pathogenic in syndromic cases and cancer including meningiomas, where they co-occur with KLF4/PIK3K-pathway mutations." (PMID 38466853, 2024). "This analysis highlighted the unique transcriptional profiles of NF2 and TRAF7 meningiomas, indicating that tumor-specific genetic alterations lead to activation of divergent signaling pathways in these tumor cells." (PMID 36937440, 2023). "The analysis revealed that meningiomas with NF2 gene inactivation expressed higher levels of BCL2 and GLI1 compared with tumors harboring TRAF7 missense mutations." (PMID 36937440, 2023). "In order to do this, the coding regions of full-length TRAF7 and meningioma mutant TRAF7N520S were expressed as fusion proteins with FLAG epitope tags at the N terminus." (PMID 37583551, 2023). "We used RNA sequencing (RNA-seq) to determine whole transcriptome profiles of twenty meningiomas with genomic alterations including NF2 inactivation, loss of chr1p, and missense mutations in TRAF7, AKT1 and KLF4." (PMID 36937440, 2023). "Next, we examined the expression of several selected TRAF7 meningioma-specific DEGs in TRAF7-/- MEFs." (PMID 36937440, 2023). "Mutations in Nf2, TRAF7, KLF4, AKT1, and SMO are present in approximately 80% of sporadic meningiomas." (PMID 37898750, 2023). "On the other hand, some mutations such as TRAF7, PI3KCA, AKT1, and SMOs are frequently observed in WHO grade 1 meningiomas and, consequently, their therapeutic potential appears somewhat limited." (PMID 37760490, 2023). "Here, TRAF7 meningiomas expressed a high number of specific DEGs, including RAPGEFL1, KRT16, KRT6A, IL1RL1, NOS1, and others." (PMID 36937440, 2023). "The authors used multi-omics data from human meningioma samples and cell lines to identify the functional roles of two genes, TRAF7 and KLF4, that are frequently mutated in meningioma." (PMID 37873876, 2023). "Here, we provide evidence that NF2-deficient meningiomas express significantly higher levels of widely recognized oncogenes BCL2 and GLI1 compared to meningiomas with missense TRAF7 mutations." (PMID 36937440, 2023). "Since the majority of TRAF7 tumors harbor a gain-of-function mutation in a single amino acid position in either AKT1 or KLF4, AKT1E17K and KLF4K409Q appear to be the driving force behind TRAF7 meningioma growth." (PMID 36937440, 2023). "PIK3CA mutations occur in about 7% of all meningiomas; they are mutually exclusive with NF2 and AKT1 and often associated with TRAF7 mutations." (PMID 38137885, 2023). "Important driver mutations specifically associated with meningioma pathology (including NF2, TRAF7, SMO, PIK3C2B and AKT1) that were identified in the tissues were consistently found in spheroids." (PMID 38102708, 2023). "The K409Q mutation in KLF4 is found in ∼15% of meningiomas, and the mutated allele KLF4K409Q is the same in all affected patients and occurs together with TRAF7 missense mutations." (PMID 35996584, 2022). "Mutations in SMARCE1, BAP1, KLF4/TRAF7, TERT promoter, and CDKN2A/B deletion, H3K27me3 loss and methylation profiling are now officially associated with the classification and grading of meningiomas." (PMID 34846640, 2022). "In their cohort of high grade meningiomas, most tumors were characterized by NF2 mutations, with very few tumors having mutations in TRAF7, KLF4, AKT1 and SMO, suggesting that high grade meningiomas have few targetable genetic mutations." (PMID 35402234, 2022).
meningioma (continued). "Because a KLF4K409Q mutation occurs exclusively in meningiomas harboring a missense TRAF7 mutation, the significance of FGF3 expression should be studied in the context of TRAF7 neomorphic function." (PMID 35996584, 2022). "Since 40-60% of sporadic meningiomas have a loss of NF2 expression, meningiomas can be molecularly categorized into NF2 mutants and non-NF2 mutants, with the latter predominantly comprised of TRAF7, KLF4, AKT1, SMO, and P13K mutations." (PMID 35712492, 2022). "Otherwise, 70% of TRAF7/AKT1-type meningiomas tend to localize in the anterior cranial fossa, at the medial portion of the middle cranial fossa, and at the level of the anterior convexity." (PMID 35892898, 2022). "TRAF7 and KLF4 mutations often co-occur in secretory meningiomas, with 40% of TRAF7-mutated meningiomas harboring a KLF4 mutation as well." (PMID 36686824, 2022). "Meningioma‐relevant mutations were present in 90/126 (71.4%) specimens including NF2, TRAF7, KLF4, SMO, AKT1,TERT promotor, ARID,SUFU, and PIK3CA mutations in similar frequencies compared to previous studies." (PMID 35213082, 2022). "Meningiomas with an AKT1 E17K mutation harbored additionally ATRX (n = 2), ARID1A (n = 2), TRAF7 (n = 1) and POLR2A (n = 1)." (PMID 35943573, 2022). "A gene involved in the growth of NF2-negative meningiomas is TRAF7, an E3 ubiquitin ligase that interacts with MEKK3/MAP3K3 (mitogen-activated protein kinase kinase 3) and regulates apoptosis." (PMID 35565385, 2022). "TRAF7 is also one of four genes including KLF4, AKT1, and SMO, likely to be mutated in non-NF2 mutated meningiomas found at the skull base." (PMID 36686824, 2022). "We; thus, performed amplicon-based single-cell DNA sequencing on 7 samples of TRAF7 with KLF4 or AKT1, respectively, co-mutated meningiomas." (PMID 35984495, 2022). "Secretory meningiomas have been defined based on combined pathogenic variants of KLF4 and TRAF7 mutually exclusive of the PI3K pathway or NF2." (PMID 33262459, 2021). "Apart from NF2 alterations in sporadic meningiomas, various oncogenic mutations in KLF4, SMO, TRAF7, PIK3CA, AKT1 and POLR2A are also found to be clinically actionable genetic events in meningiomas." (PMID 34722286, 2021). "Two independent studies have identified TRAF7 (TNF receptor-associated factor 7), AKT1 (v-akt murine thymoma viral oncogene homolog 1), and SMO (Smoothened, frizzled family receptor) mutations as drivers of meningioma oncogenesis." (PMID 34300316, 2021). "While each gene variant has provided further information on the biology of meningioma; monosomy, NF2 and TRAF7 seem to be the driving forces in tumorigenesis." (PMID 33346248, 2020). "Each subtype of meningiomas has its own molecular features, but some genetic mutations (including NF2, TRAF7, AKT1, and PIK3CA) can be found among several subtypes of meningiomas, which confuse the judgment of tumor evolution." (PMID 33014773, 2020). "Tumors with mutations in both TRAF7 and KLF4 are most often found in secretory meningiomas with TRAF7 mutant tumors having a predilection for the anterior skull base." (PMID 33346248, 2020). "In the present study, all the sample groups had mutations in the meningioma-driver genes such as NF2, AKT1, SMO, TRAF7, and KLF4." (PMID 32742192, 2020). "Exclusive of TRAF7, AKT1, PIK3CA, KFL4, and SMO, mutations in POLR2A, which encodes DNA-directed RNA polymerase II subunit RPB1, are found in 6% of meningiomas." (PMID 31970090, 2019). "Recently, alterations in other oncogenic genes such as TRAF7, AKT1, KLF4, PIK3CA, SMO, and DMD have also been implicated in meningioma etiology." (PMID 31191822, 2019). "The tumor suppressor TRAF7, which exclusively occurs in non-NF2 meningiomas, is the second most altered gene with mutations occurring in approximately 25% of cases." (PMID 31470906, 2019).